MIR147B (microRNA 147b)
Synonyms: hsa-mir-147b; MIRN147B; mir-147b
Gene: MicroRNA gene on chromosome 15 (45,433,050 to 45,433,129, forward strand). Ensembl gene ENSG00000284386.
Gene Ontology:
Biological process: miRNA-mediated post-transcriptional gene silencing
Cellular component: RISC complex
Homologues: Orthologues: chimpanzee ptr-mir-147b (100% identical), macaque mml-mir-147b (96% identical), dog MIR147 (95% identical), mouse Mir147 (91% identical), rat Mir147 (90% identical), guinea pig MIR147B (84% identical), rabbit MIR147B (66% identical).